IL6 (interleukin 6)
Diseases named in the same sentence as IL6 in open-access papers (continued):
Sharing a sentence is not in itself a finding about the gene and the disease.
juvenile idiopathic arthritis (103 papers, 2008 to 2026). Juvenile idiopathic arthritis (JIA) is the term used to describe a group of inflammatory articular disorders of unknown cause that begin before the age of 16 and last over 6 weeks. "It has been reported that the C allele of − 174 G/C IL-6 gene polymorphism was associated with significantly lower IL-6 level in control group than juvenile arthritis." (PMID 32270320, 2021). "In accordance with the pathogenic role of IL-6 in autoimmune and chronic inflammatory diseases such as RA and juvenile idiopathic arthritis, the IL-6 signaling cascade has been targeted in numerous inflammatory diseases." (PMID 33334075, 2020). "The C-174G promoter polymorphism of the IL-6 gene has been established to control transcriptional regulation and has been associated with plasma IL-6 levels in patients with systemic-onset juvenile chronic arthritis and in patients with primary Sjögren’s syndrome." (PMID 29182577, 2017). "Several polymorphisms have been revealed in the IL-6 gene, including one of the most important single-nucleotide polymorphisms (SNPs) in the promoter, the -174G to C substitution, which affect IL-6 levels and are associated with RA, especially with systemic juvenile chronic arthritis." (PMID 24707478, 2014). "In juvenile idiopathic arthritis (JIA), excessive production of IL-6 and IL-1β (for systemic JIA) has been implicated in their pathogenesis." (PMID 25344730, 2014). "Management of systemic juvenile idiopathic arthritis, or Still’s disease, has been transformed by the introduction of IL-1 and IL-6 antagonists." (PMID 41281302, 2025). "The main risk factors are already known, such as macrophage activation syndrome, a refractory course of systemic juvenile arthritis, infusion reaction to interleukin 1 and/or interleukin 6 blockers, trisomy 21, and eosinophilia." (PMID 38999409, 2024). "Interleukin-6 (IL-6) is a proinflammatory cytokine that significantly contributes to both the articular and extra-articular manifestations of juvenile idiopathic arthritis (JIA), as well as to the chronic complications associated with the disease." (PMID 39311914, 2024). "IL-6 plays a role in immunogenicity and inflammation in both systemic and ocular immune-mediated diseases, including juvenile idiopathic arthritis and NIU." (PMID 36902105, 2023). "Grevich S, Shenoi S. Update on the management of systemic juvenile idiopathic arthritis and role of IL-1 and IL-6 inhibition." (PMID 37848930, 2023). "We also identified a strong positive correlation between plasma levels of eNAMPT, IL-1RA, and IL-6 levels, a novel finding in sarcoidosis, previously reported in juvenile idiopathic arthritis." (PMID 36388923, 2022). "Recent literature also points out that co-culture of UC-MSCs can prevent the differentiation of naive T cells into Th17 cells and treat persons with juvenile idiopathic arthritis (JIA) by downregulating the level of TNF-αand IL-6." (PMID 36552891, 2022). "Tocilizumab, a humanized antihuman IL-6 receptor antibody that inhibits IL-6 activity, is already an effective treatment of juvenile idiopathic arthritis and other rheumatological diseases." (PMID 33344389, 2020). "IL-6 blockade has been successfully used in Castelman’s disease, a lymphoproliferative disorder with a wide spectrum of manifestations, and juvenile idiopathic arthritis (JIA)." (PMID 32718086, 2020). "An antagonist of IL-6 is tocilizumab, previously approved to treat juvenile idiopathic arthritis which is a rheumatic condition, is again “repurposed” for the COVID-19 pandemic." (PMID 32850977, 2020). "Inhibition of IL-6 interactions has now surfaced as an importantdrug target against Juvenile Idiopathic Arthritis." (PMID 31435158, 2019). "The objective is to measure the impact of a single bout of exercise on plasma inflammatory markers such as calprotectin, IL-6, sIL-6R, sgp130, and the hypothalamic-pituitary-adrenal axis in children with juvenile idiopathic arthritis." (PMID 30008613, 2018).
juvenile idiopathic arthritis (continued). "Overproduction of IL-6 can cause various symptoms, including fever and lymphadenopathy, and has been associated with autoimmune disorders, such as RA and juvenile idiopathic arthritis (JIA), as well as lymphoid malignancies." (PMID 26697019, 2015). "Pain and inflammation symptoms are known to be related to IL-6, and it was recently reported by Oen and coworkers that the promoter genotype -174GG has a positive correlation with pain in juvenile rheumatoid arthritis." (PMID 18257935, 2008). "The role of TCZ in addressing the interleukin-6-mediated inflammatory pathways has been well-established in the field of rheumatological diseases, including rheumatoid arthritis, juvenile idiopathic arthritis (JIA), giant cell arteritis or cytokine release syndrome." (PMID 39570440, 2024). "Notably, Tocilizumab has shown its effectiveness in a range of inflammatory diseases in which IL-6 signaling plays a role, such as rheumatoid and juvenile idiopathic arthritis." (PMID 38062491, 2023). "Tocilizumab, a monoclonal antibody against IL-6 is used in the treatment of juvenile idiopathic arthritis and autoinflammatory diseases, such as familial Mediterranean fever, cryopyrin-associated periodic syndrome, and tumor necrosis factor receptor-associated periodic syndrome." (PMID 37828538, 2023). "The decreased plasma level may be caused by proteolytic degradation of IGF-1 binding protein-3 resulting in an increased clearance of IGF-1, as previously shown in a model of juvenile arthritis induced by IL-6 overexpression." (PMID 35388142, 2022). "If this evidence will be confirmed, agents neutralizing IL-1 and IL-6 may be effective in treating PP, similarly to juvenile idiopathic arthritis, which has been successfully treated with either anti-IL-1 agents or IL-6 inhibitors." (PMID 25126586, 2014). "In juvenile idiopathic arthritis (JIA), the most common rheumatoid disorder in pediatrics, an elevation of proinflammatory cytokines, such as IL-1β, IL-6, IL-8, or TNF-α, has been demonstrated in both the serum and synovial fluid of patients with JIA." (PMID 31118902, 2019). "Elevated levels of IL-6 have been observed in pathological conditions including RA, juvenile idiopathic arthritis (JIA), IBD, allergic asthma, multiple sclerosis, and serum lupus erythematosus (SLE)." (PMID 29662489, 2018). "Aberrant expression of IL-6 has been indicated in inflammatory diseases such as RA and juvenile idiopathic arthritis (JIA), leading to the development of a humanized IL-6 receptor." (PMID 25873919, 2015). "Central to the pathogenesis of juvenile idiopathic arthritis is immune dysregulation, which leads to excessive production of proinflammatory cytokines (TNF-α, IL-1, IL-6, IL-17)." (PMID 41465591, 2025). "The CARRA protocols will be evaluated during the FiRst-line Options for Systemic juvenile idiopathic arthritis Treatment (FROST) study, comparing CO, MTX, IL-1i, and IL-6 blockade." (PMID 33752669, 2021). "Nevertheless, recent data showed that booster MMR vaccine in patients with juvenile idiopathic arthritis receiving bDMARDs (anti-TNFα, anti-IL-1, or anti-IL-6) is safe and immunogenic, with no patients developing a disease flare." (PMID 37439850, 2023). "Notably, the reduction effect of canakinumab on the concentrations of IL-1RA, IL-6, IL-18 and S100A12 in our cohort had been confirmed recently in a systemic juvenile idiopathic arthritis cohort." (PMID 34640417, 2021).
ulcer (103 papers, 2007 to 2026). "TNF-α is also a powerful ulcer-causing medium that can promote the secondary release of other cytokines including IL-1, IL-6, IL-8, PAF, and PGs." (PMID 30719066, 2019). "The oxidative pathways which causes tissue damages during ulcer results from lymphocytes and neutrophils which are stimulated by the increased levels of IL-6." (PMID 26694339, 2015). "Through the paracrine pathway, the system suppresses the expression of inflammatory factors such as IL-6, promotes the upregulation of associated growth factors, and improves ulcer tissue vascularization in murine dorsal regions, thereby accelerating wound healing." (PMID 37370102, 2023). "The current results showed that the EtOH-induced ulcer group had considerably greater levels of gastric IL-6, consistent with earlier research on the pro-inflammatory action of EtOH." (PMID 40644360, 2025). "They found that factors such as disease perception, ulcer duration, and biochemical markers (e.g., IL-6, microRNA-146a-5p, PECAM-1, and angiopoietin-2) had substantial predictive value for healing outcomes." (PMID 40620799, 2025). "Chrysin oral gel (1% and 2%) application for 7 days decreased buccal contents of TNF-α by 51% and 71%, NF-κβ by 22% and 60%, and IL-6 by 49% and 78%, respectively, as compared to the ulcer group." (PMID 40809172, 2025). "The group that received cranberry treatment (G4) demonstrated a noteworthy reduction in the levels of TNF-α and IL-6 when compared to the levels that were observed in the group that was subjected to Indomethacin ulcer induction (G2)." (PMID 40469801, 2025). "Regarding the Omeprazole treatment group, there was a significant decrease in TNF-α and IL-6 levels compared to the ulcer induction group (G2)." (PMID 40469801, 2025). "The levels of pro-inflammatory factors such as NF-κB, TNF-α, and IL-6, which trigger inflammation and slow ulcer healing, also increase with ethanol consumption." (PMID 40244034, 2025). "The reference rats showed a better serum inflammatory profile (lower TNF‐α, and IL‐6 levels and increased IL‐10 cytokines) than the ulcer controls." (PMID 40034223, 2025). "IL-6 levels were highest in the ulcer group (9.3 ± 2.5 pg/mL) compared to pre-ulcer (4.8 ± 1.2 pg/mL) and control (2.1 ± 0.5 pg/mL) groups." (PMID 40364880, 2025). "These inflammatory mediators heighten the risk of GIB through two primary mechanisms: TNF-α promotes endothelial cell apoptosis and microvascular remodeling, whereas IL-6 impedes ulcer healing." (PMID 40687126, 2025). "Compared to the ulcer group, the Cls and Omp groups had significant reductions in IL-1β, IL-6, and TNF-α contents." (PMID 38884677, 2024). "Rats treated with Schiff base compound meaningfully condensed TNF-α and IL-6, increased IL-10 quantities, and related ulcer control group." (PMID 39830532, 2024). "AA showed severe macroscopic colonic lesions associated with increased ulcer number, area, and severity with significantly elevated PI3K, p-Akt, Nrf2, TNF-α, and IL-6 in colorectal tissue as compared to the normal control group." (PMID 38645494, 2024). "This study emphasizes the ability of PRF-EMFs to modulate the TGFβ, COX2, IL6, IL1β, and TNFα gene expression in exposed ulcers." (PMID 38671778, 2024). "As a result, suppressing the expression of pro-inflammatory cytokines such as TNF-α, IL-1β, and IL-6 effectively treats ulcer damage in the colon." (PMID 38791116, 2024). "In agreement with the literature, a more intense expression of COX2, IL1β, IL6, TGFβ, and TNFα was observed in ulcer-HDFs than in normal-HDFs." (PMID 38671778, 2024). "It has been established that EGF, VEGF, IL-6, and TNF-α are crucial factors in the development of gastric ulcers, and their levels are associated with the healing or deterioration of these ulcers." (PMID 38398633, 2024). "TNF-α, IL-6, and IL-10 are significantly higher in ulcer control group compared to the fed with omeprazole or Schiff base compound." (PMID 39830532, 2024).
ulcer (continued). "It regulates expression of genes of the inflammatory pathway like TNF-α and IL-6, increasing inflammation and extension of ulcer injury." (PMID 37255094, 2023). "As IL-6 mediates the amount of hepcidin and consequent hypoferremia during inflammation, IL-6 mRNA levels in the ulcer region were investigated in the OUM model." (PMID 37079608, 2023). "While the group treated with ZJP (1, 2, and 4 g/kg) displayed a noteworthy decrease in TNF-α and IL-6 content (P < 0.01) in a dose-dependent mode referred to ulcer model group." (PMID 35938492, 2022). "TNF-α and IL-6 apparently rose by 58.8% and 68.1% in the ulcer control group compared to those in the normal control group (p < 0.01)." (PMID 35938492, 2022). "The results demonstrated that ZJP suppressed the inflammatory response to alleviate ulcers in gastric tissue by decreasing the content of TNF-α and IL-6 and restraining neutrophil infiltration of the ulcer gastric tissue." (PMID 35938492, 2022). "For mice that were treated with EGb 761 orally following indomethacin-induced ulcerations, the levels of TNF-α (173.7 ± 10.98 pg/mL, p < 0.001) and the levels of IL-6 (188.8 ± 21.71 ng/L, p < 0.01) were considerably lowered as compared to the ulcer group." (PMID 36080365, 2022). "High (H-PPT) and medium (M-PPT) doses of PPT (20.0 and 10.0 mg/mg/day) significantly reduced the ulcer area and the ET-1, IL-6, EGF, SOD, MDA and TNF-α levels in serum were regulated by PPT in a dose-dependent manner." (PMID 36292949, 2022). "To evaluate the anti-inflammation of the AAEs in ulcers, we detected the levels of proinflammatory and anti-inflammatory cytokines, including IL-1β, IL-6, and IL-10 in the serum." (PMID 34580595, 2021). "The mechanisms of gastric injury have not been fully clarified, but it is well known that proinflammatory mediators played an important role in the development of ulcer, including IL-6, IL-10, tumor necrosis factor-α (TNF-α), and NF-κB." (PMID 34580595, 2021). "On the other hand, KHGs alleviated the symptoms of the gastric ethanol-induced ulcer including the bleeding, oedema, ulcer with macroscopy and abnormal expression of IL-6, MDA and SOD." (PMID 33738122, 2021). "F-AOH effectively reduced the ulcer index (from 23.4 ± 4.28 to 8.32 ± 1.5) and reduced release of inflammatory mediators (IL-1β, IL-6, TNF-α and PGE2), increased the content of nitric oxide and improved GAS and MTL secretion." (PMID 32871094, 2020). "Mixed cell implantation in this ulcer model reduced TNF-α and IL-6 levels in the tissues surrounding the mixed cell sheet-treated ulcers compared with controls or mice treated with trafermin (FGF2)." (PMID 28687753, 2017). "Unlike exogenous growth factor interventions, harnessing endogenous NO for healing aligns more closely with physiological processes, also it can effectively remove pro‐inflammatory factors such as TNF‐α and IL‐6, illuminating its significant potential in advancing ulcer healing therapies." (PMID 40548949, 2025). "In addition, sodium butyrate significantly inhibited the mRNA levels of inflammatory factors such as tumor necrosis factor-α (TNF-α), interleukin-1β (IL-1β), interleukin-6 (IL-6), and interleukin-18 (IL-18) in the ulcer tissue." (PMID 40818135, 2025). "Our findings corroborate earlier research indicating that OMP, used as a reference drug, significantly diminished the levels of HMGB1, NF-κB p65, and NLRP3 in comparison to the ulcer group and substantially reduced the levels of IL-1β, IL-6, and TNF-α in gastric mucosa." (PMID 40563542, 2025). "Juglans regia L. obviously improved HAG condition (edema, erythema, inflammation, ulcer) and subsequent disease deterioration (ulcer, atrophy, tumor, pale and thin mucosa), which accompanied lower production of IL-6, COX-2/COX-1, PGE2, c-Fos, c-Jun, c-Myc, p-p65, and pSTAT3." (PMID 40264171, 2025).
ulcer (continued). "Accumulation of visceral adipose tissue has been reported to promote the secretion of pro-inflammatory cytokines such as IL-6, thereby activating the NF-κB signaling pathway, impairing fibroblast migration and angiogenesis, and ultimately delaying ulcer healing." (PMID 40620796, 2025). "These trials have faced challenges and side effects in patients with gastrointestinal perforations and ulcers, for example, all of which highlight the dual role of IL-6 during intestinal inflammation and the need for this cytokine for intestinal tissue integrity." (PMID 38106420, 2023). "However, this is the first time that the inhibitory effects of FA treatment on gastric TNF-α and IL-6 levels have been demonstrated in an indomethacin-induced ulcer." (PMID 36836745, 2023). "As suggested before, IL-6 levels increase in indomethacin-induced ulcers." (PMID 36836745, 2023). "Additionally, when EGb 761 was administered following ulcer induction, IL-6 expression was likewise dramatically decreased." (PMID 36080365, 2022). "Another investigation using a mouse model of ethanol-induced ulcer found that pretreatment with oral ORV reduced ulcer scores and ulcer index, as determined from the increased gastric pH and the decreased expression levels of IL-6, TNF-α, NF-ĸB, and COX-2, with unaltered COX-1 expression levels." (PMID 34299485, 2021). "Since a decreased production of IL-6 in the oral mucosa is thought to drive rapid oral mucosal healing its presence in BD-MA could perpetuate the ulcer." (PMID 35003055, 2021). "In addition, it can also reduce the expression of CD14 and IL-6 in colonic mucosa and alleviate the severity of ulcers." (PMID 34692749, 2021). "In addition, ulcers in diabetic patients show a complete derangement of inflammation mediators: interleukin (IL)-1β, IL-6, tumor necrosis factor-α (TNF-α)." (PMID 33227909, 2020). "Similarly, IL-6 expression was significantly lower only in the skin around cell sheet-treated ulcers than in controls (P < 0.05)." (PMID 28687753, 2017). "Pretreatment of ethanol-injected rats with both omeprazole and manuka honey caused a significant decrease in plasma TNF-α (38% and 28%) (P = 0.000 and 0.000), IL-1β (49% and 50%) (P = 0.000 and 0.000), and IL-6 (45% and 47%) (P = 0.000 and 0.000) as compared to the ulcer-induced rats." (PMID 26770649, 2016). "However, only PS reduced NO, TNF-α, and IL-6 levels, which were upregulated in this ulcer model." (PMID 36712695, 2022). "The results indicated a strong positive correlation between inflammatory biomarkers (IL-6, TNF-α, CRP) and HbA1c and ulcer severity, suggesting that increased systemic inflammation is associated with poor glycemic control and worsening ulcer conditions." (PMID 40364880, 2025). "DFU induces marked upregulation of inflammatory markers such as TNF-α, IL-6 and CRP, which correlate with ulcer severity." (PMID 39508881, 2025). "Serum levels of IL-6, TNF-α, and CRP showed a progressive increase from the control group to the ulcer group, with statistically significant differences (p < 0.001)." (PMID 40364880, 2025). "Our study revealed a significant increase in IL-6, TNF-α, and CRP levels in ulcer patients compared to the pre-ulcer and control groups." (PMID 40364880, 2025). "The mechanisms of gastric injury have not been fully clarified, but it is well known that pro-inflammatory mediators, including IL-6, IL-12, TNF-α, and NF-κB, play an important role in the development of ulcers." (PMID 40283949, 2025). "Data were collected on demographics, ulcer severity (Wagner Grade), glycemic status (HbA1c), biochemical markers (C-reactive protein [CRP], interleukin-6 [IL-6], tumor necrosis factor-alpha [TNF-α], and serum albumin), and clinical outcomes." (PMID 40821188, 2025). "mRNA levels of IL-1β, IL-6, IL-18, and TNF-α in the ulcer tissue were significantly reduced following butyrate treatment, while the levels of tight junction proteins Claudin-1 and ZO-1 were significantly elevated." (PMID 40818135, 2025).